DISC1 (DISC1 scaffold protein)
Diseases named in the same sentence as DISC1 in open-access papers (continued):
Sharing a sentence is not in itself a finding about the gene and the disease.
schizophrenia (continued). "As recently discussed elsewhere, despite its name, ‘disrupted in schizophrenia 1’, DISC1 may not be a key risk factor for schizophrenia." (PMID 24712987, 2014). "Identifying the key DISC1 interactors is therefore of exceptional importance in coming to understand the nature of the devastating condition that is schizophrenia, and will facilitate the search for downstream elements which may be susceptible to pharmaceutical intervention." (PMID 21195721, 2012). "To date, studies on brain samples of individuals with schizophrenia, MDD, and bipolar disorder have demonstrated the presence of insoluble aggregates of the DISC1 protein." (PMID 41465140, 2025). "Proteins such as DISC1, CRMP1, NOS1AP, and others have been identified with altered expression and aggregation patterns in schizophrenia, linking protein abnormalities to disease pathology." (PMID 41217487, 2025). "The genetic factors disrupted in schizophrenia 1 (DISC1) and PDE4 collaborate to regulate cAMP signaling in schizophrenia." (PMID 37605207, 2023). "To mimic pathological changes in schizophrenia patients, we generated a DISC1exon3 flox mouse strain, and crossed it with the OPC-specific NG2CreERT mice to obtain NG2CreERT:DISC1exon3 fl/+ (DISC1-Δ3) mice." (PMID 36131044, 2022). "The dopamine hypothesis, the current leading theory of the pathogenesis of schizophrenia, is supported by genetic studies indicating that single nucleotide variations (SNVs) related to dopaminergic transmission, such as DRD2, COMT, DISC1, and PCLO, are associated with a higher risk of schizophrenia." (PMID 34063598, 2021). "The levels of DISC-1 and TDP-43, 2 molecules related to schizophrenia and amyotrophic lateral sclerosis–frontal temporal dementia were unchanged in both hippocampal and neocortical tissues of Ndel1 CKO mice when compared with those of WT littermates." (PMID 33615226, 2021). "Particularly, the interaction between disrupted in schizophrenia 1 (DISC1) and NDE1’s NUDE-C domain has been shown and has garnered attention, as it potentially relates NDE1 to schizophrenia." (PMID 33390896, 2020). "Although genome-wide analyses for schizophrenia failed to provide support for DISC1 itself as a common risk gene for schizophrenia, a large set of DISC1-interacting proteins (DISC1 interactome) have disruptive variants that are significantly associated with low cognitive ability in schizophrenia." (PMID 32796766, 2020). "It is with great interest we have read the article “GLYX-13 Ameliorates Schizophrenia-Like Phenotype Induced by MK-801 in Mice: Role of Hippocampal NR2B and DISC1”." (PMID 30233316, 2018). "This lncRNA has been shown to modulate expression of genes involved in schizophrenia such as CSMD1 and DISC1." (PMID 27913161, 2017). "Using Disrupted-in-schizophrenia-1 gene (Disc1) mutant mice combined with MIA, in vivo evidence for the interaction of gene and prenatal environment in the pathogenesis of schizophrenia and depression was also provided." (PMID 26074774, 2015). "It has been proposed that aggresome formation may cause a loss of function of DISC1 by disrupting its interaction with partners, such as nuclear distribution element-like (NDEL1/NUDEL), or by impairing mitochondria transport and function, which may have a role in the pathogenesis of schizophrenia." (PMID 27462430, 2015). "Post-mortem brain analyses and some genetic studies have reported interneuronal deficits and involvement of the DISC1, NRG1 and ErbB4 genes in schizophrenia, respectively." (PMID 26656849, 2015). "Although no stress-induced psychiatry disorder has so far been associated with changes in Chchd6 gene expression, dysfunction of MICOS and OXPHOS impairment were found in neuronal cells lacking Disc1 (disrupted in Schizophrenia-1) gene." (PMID 37978166, 2023). "Current genetic findings have compromised the earlier studies of employing the DISC1 transgenic models, as it fails to reflect most of the symptoms of schizophrenia." (PMID 36692676, 2023).
schizophrenia (continued). "DISC1 is a scaffold protein with a highly complex interactome at the PSD site and is involved in multiple brain functions relevant to the symptomatology and pathophysiology of schizophrenia." (PMID 36831241, 2023). "By selecting SNPs associated with the schizophrenia and infant right frontal lobe white matter volume in our cohort, we identified genes overrepresented for pathways involved in neuron development, many of which have previously been validated in schizophrenia models (e.g., ZNF804A, DISC1, NRXN3)." (PMID 37037832, 2023). "In rodent models of schizophrenia, some studies reported a weaker hippocampal LTP after social isolation, deletion of dysbidin-1, or treatment with the NMDAr antagonist MK801, whereas an increase in LTP has been reported after deletion of DISC1." (PMID 33807989, 2021). "As GOMAFU was found to be downregulated in post-mortem cortical tissue from the superior temporal gyrus of schizophrenia patients, the aberrant splicing patterns of DISC1 and ERBB4 in schizophrenia are suggested to be a consequence of disturbed GOMAFU expression." (PMID 31698782, 2019). "In order to address these issues, we combined a DISC1-transgenic animal model with juvenile immune activation (JIA) in male and female rats to induce a behavioral phenotype relevant to schizophrenia, as well as to investigate possible effects of sex on the phenotype." (PMID 31057438, 2019). "Irrespective of its role in schizophrenia, studies on DISC1 have revealed this molecule to be of fundamental importance in many neuronal processes including synaptic plasticity, dendritic growth and intracellular trafficking." (PMID 30008190, 2018). "Ppy-DBSA combined with electrical stimulation may therefore correct impaired neurite growth arising from gene dysregulation relevant to schizophrenia, such as NRG1 and DISC1 haploinsufficiency." (PMID 28198409, 2017). "Since in schizophrenia baseline occupancy of D2 receptors by dopamine is increased and the CAD cell line expresses D1, D2, D3 and D5 dopamine receptors, one possible explanation is that dopamine promotes faster DISC1 aggregation via the D2 receptor." (PMID 28275106, 2017). "DISC1 (disrupted-in-schizophrenia 1) has been studied extensively in relation to mental disease while CTXN3, has only recently emerged as a potential “candidate” gene in schizophrenia." (PMID 25889058, 2015). "Changes in cortexin 3/DISC1/APP interactions could, therefore, result in altered expression and distribution of NMDA receptors as has been observed in schizophrenia (review:)." (PMID 25889058, 2015). "Similarly, studies of DISC1 knockout mice and neuregulin 1 (NRG1) knockout mice as models for schizophrenia initially focused on the role these proteins play in neurons, but more recently, their activities in glial cells have begun to be considered." (PMID 26029044, 2015). "Mice lacking exons 2 and 3 of the disrupted-in-schizophrenia (DISC1) gene displayed schizophrenia-relevant behaviors, similarly to our ZFP521 mutant mice." (PMID 24676388, 2014). "Here, users can construct queries such as “DISC1 but not immunity”, “interactions of any of these proteins: TLR1, TLR2...”, “genes associated with schizophrenia that interact with genes associated with immunity” and so on." (PMID 23209562, 2012). "Of the 34 carriers of the DISC1 genetic abnormality, 16 had various psychiatric diagnoses ranging from schizophrenia to alcoholism; there were also 5 of the 43 noncarrier family members who had a psychiatric diagnosis." (PMID 23074677, 2011). "In the Disc1 mutant mouse, L100P, which lies with a missense PDE4B-specific binding site in exon 2, rolipram treatment improves the behavioural and cognitive deficits seen in this model of schizophrenia." (PMID 21298101, 2011). "It is therefore unclear whether the overlap on the effects of disruption of DISC1 and HTT overlap within the domains of depression or schizophrenia." (PMID 21298101, 2011).
schizophrenia (continued). "Either way, our updated network analysis provides strong evidence for a link between DISC1 and HTT, and thus implies a degree of biological commonality between the neurological disorders of Huntington's disease and of schizophrenia and related major psychiatric illness." (PMID 21298101, 2011). "The function of the DISC1 gene or its mechanistic role in schizophrenia is still not fully known and current research is focusing on filling this knowledge gap." (PMID 19128481, 2009). "For example, in the DISC1(disrupted-in-schizophrenia 1) model, which is the candidate gene locus first described in a large Scottish family, NPY-immunoreactive neurons expressions in the prefrontal lobes of DISC1-knockout mice were decreased compared to wild type." (PMID 39691787, 2024). "Schizophrenia subjects exhibited thousands of neuronal and non-neuronal epigenetic differences at regions that included several susceptibility genetic loci, such as NRG1, DISC1, and DRD3." (PMID 38648100, 2024). "DISC1-Δ3 transcript translates into a short DISC1 protein isoform lacking the binding sites with several protein partners, yet little is known of its role in oligodendroglia or in the pathogenesis of schizophrenia." (PMID 36131044, 2022). "Thus, in much the same way as DISC1 was discovered at a translocation breakpoint, PDE4B was found to be directly disrupted by a t(1:16) translocation in a proband with schizophrenia, who also had an affected cousin." (PMID 21195721, 2012). "Autoantibodies to DISC1 have not been reported in schizophrenia." (PMID 22567321, 2011). "In various studies, only a few of them, such as DISC1 (Disrupted-In-Schizophrenia 1), COMT (Catechol-O-Methyltransferase), VMAT1 (Vesicular Monoamine Transporter 1) or NRG1 (Neuregulin 1), could be sufficiently confirmed as relevant for schizophrenia development." (PMID 35053755, 2021).
depression (65 papers, 2011 to 2026). "DISC1 has been linked to a range of mental illnesses, including schizophrenia, bipolar disorder, and major depression." (PMID 39194719, 2024). "DISC1 mutations, as well as mutations p62, the most common genetic component, have been associated with depression." (PMID 33918863, 2021). "DISC1 variants (haplotypes, single nucleotide polymorphisms and copy number variations) have since been independently associated with depression, schizophrenia, bipolar disorders and autism spectrum disorders." (PMID 27378904, 2016). "N-ethyl-N-nitrosourea (ENU)-induced inheritable missense point mutations in exon 2 of the mouse DISC1 gene have been of particular interest since Q31L mutant mice showed depression-like behaviors while L100P mutants showed schizophrenia-like phenotypes." (PMID 27729083, 2016). "Lesions and mutations of the DISC1 (Disrupted-in-schizophrenia-1) gene have been linked to major depression, schizophrenia, bipolar disorder and autism, but the influence of DISC1 on synaptic transmission remains poorly understood." (PMID 27378904, 2016). "While MIA has not yet been associated with depression in humans, MIA interacted with DISC1 mouse models to generate depression-like behaviors." (PMID 25762938, 2015). "Our results demonstrate that a mutation in a high risk gene for depression, the DISC1 truncation correlates with reduced synchrony of theta and low-gamma oscillations in the PrlC." (PMID 25735038, 2015). "For example, mutations in Disrupted in Schizophrenia 1 (Disc1) can lead to schizophrenia, bipolar disorder, major depressive disorder, and autism." (PMID 23637652, 2013). "Furthermore, DISC1 mutations have been found to be associated with other neurological disorders, such as bipolar disorder and depression, stressing the functional and genetic overlap among those diseases." (PMID 33918863, 2021). "DISC1 (Disrupted in schizophrenia 1) plays important roles in cell migration and dendrite development, and it has been linked to schizophrenia, bipolar disorder, depression, and ASDs." (PMID 29345619, 2018). "Nevertheless, it suggests that further studies are needed to elucidate the cause of behavioral variance associated with DISC1 L100P or Q31L mutants and to determine whether these mice strains are suitable animal models to study schizophrenia and depression." (PMID 27729083, 2016). "Disrupted-in-schizophrenia 1(DISC1) is a promising candidate susceptibility gene for a spectrum of psychiatric illnesses that share cognitive impairments in common, including schizophrenia, bipolar disorder and major depression." (PMID 27729083, 2016). "To obtain deeper insight into the pathophysiology of Disc1-associated behavioural despair, we next focussed on the mechanisms underlying impaired low-gamma oscillations in the PrlC because human depression patients show reduced low-gamma activity in frontal regions." (PMID 25735038, 2015). "Similarly, cg04897932, which is hypomethylated in affected twins (Δβ = −.04, p = .0002), is located upstream of NDEL1, which forms a complex with DISC1, an established risk gene for several psychiatric conditions including major depression." (PMID 24929637, 2014). "Sex differences in HRM/DISC1 mice are likely present, and have been reported in both individual HRM and DISC1 models, including cognitive deficits and depression exclusive to female DISC1 mutant mice." (PMID 38283751, 2023). "The mutant expression of DISC1 produced more anxious and depression-like behavior and reduced social exploration in the social chamber test as well as less proliferation of neural progenitors and dendritic maturation in the DG." (PMID 36407114, 2022). "Previous genetic studies have associated DISC1 and a neighboring gene (translin-associated factor X, TSNAX) with multiple mental disorders (e.g., schizophrenia, bipolar spectrum disorder, and major depressive disorder)." (PMID 30285728, 2018).
depression (continued). "DISC1 was initially identified in a large Scottish family with a spectrum of mental diseases (including schizophrenia, recurrent major depression and bipolar disorder)." (PMID 30285728, 2018). "Different mouse models have reported that DISC1 is involved in synapse function and related to neurological diseases such as depression." (PMID 28331639, 2017). "Our Nes-DN-DISC1 mice show changes in anxious and depression behaviors, which are consistent with recent genetic finding of an association of DISC1 with MDD." (PMID 29156684, 2017). "As DISC1 variants have been associated with MDD, we examined if Nes-DN-DISC1 mice show any depression-like behaviors using FST and NSF tests." (PMID 29156684, 2017). "Here we report that DISC1 L100P homozygous mutant shows normal anxiety- and depression-like behavior, but impaired object recognition which is prevented by administration of atypical antipsychotic drug clozapine." (PMID 27729083, 2016). "We find that mice expressing truncated Disrupted-in-Schizophrenia 1 (Disc1), which mirror a high-prevalence genotype for human psychiatric illness, show depression-related behavior." (PMID 25735038, 2015). "One of the most intensely studied schizophrenia-related genes is DISC1, which was first identified in a Scottish pedigree displaying high incidence of depression, schizophrenia, and bipolar disorder." (PMID 23637652, 2013). "In the context of promoting resilience to depression, the increase in Disc1 transcription in response to chronic stress could reflect an effort to manage the demands of its expansive interactome." (PMID 37228107, 2023). "Thus, Disc1 mice showed a specific phenotype broadly interpreted as depression-related behavioural despair." (PMID 25735038, 2015). "Another genetic mutation that has received a great deal of attention occurs in the gene Disrupted-in-Schizophrenia 1 (DISC1) and was found to co-segregate with psychiatric illness including schizophrenia, bipolar disorder and depression in a large Scottish family." (PMID 26858612, 2015). "Initially, we focussed on proteins encoded for by known mental illness risk genes, and by this approach identified both Disrupted-In-Schizophrenia 1 (DISC1) and dysbindin as showing aberrant aggregation in a subset of patients with schizophrenia, bipolar disorder or major recurrent depression." (PMID 25333879, 2014). "Recent studies, however, have shown that at least some mental illnesses may result from mutations in single genes including Disrupted in Schizophrenia-1 (DISC-1), which was first identified in a large Scottish family with high rates of schizophrenia, bipolar disorder, and depression." (PMID 27630583, 2016). "Thus, truncation of DISC1 in human patients may contribute to the development of depression by affecting anatomical and physiological properties of prefrontal PV-FS-INs." (PMID 25735038, 2015). "In addition, our finding suggested that social isolation from 5 weeks to 8 weeks of age may not be adverse enough to affect anxiety- or depression- like behaviors even when combined with DISC1 L100P point mutation." (PMID 30116177, 2018). "We find that Disc1 mice show increased immobility during the tail-suspension (TST) and forced swim test broadly accepted as depression-related behavioural changes in rodents." (PMID 25735038, 2015). "However, other independent research groups recently reported that no typical schizophrenia-like or depression-like behaviors were observed in DISC1 L100P or Q31L mutants respectively." (PMID 27729083, 2016). "The 15 target genes include DYNLT1, GCH1, TOR1B, DISC1, MEF2A and ST3GAL5 that to date were never related to an IFN-α regulation while all of them have been described in association with brain development or depression." (PMID 22701688, 2012).
bipolar disorder (62 papers, 2005 to 2025). A disorder of the brain that causes unusual shifts in mood, energy, activity levels and the ability to carry out day-to-day tasks. "Mutations of disrupted-in-schizophrenia 1 (DISC1) are known to be associated with major psychiatric disorders, such as schizophrenia, autism, bipolar disorder, and depression." (PMID 29937727, 2018). "DCTN5 also interacts with DISC1 gene (Disrupted in schizophrenia 1), a gene associated with bipolar disorder in several studies." (PMID 28283021, 2017). "Variations in Disrupted in Schizophrenia 1 (DISC1) gene is implicated in major neuropsychiatric disorders (NPs), such as schizophrenia, bipolar disorder, depression and autism." (PMID 25139375, 2014). "There are overlapping GM structural abnormalities in the neurobiology of schizophrenia and bipolar disorder and there are several susceptibility genes (e.g., DISC1) for both of these disorders." (PMID 25105667, 2014). "Based on their results, the DISC1 expression was correlated with an enhanced bipolar disorder (BD) risk, which may be due to DNA methylation, and it may be associated with BD neurobiology." (PMID 37744384, 2023). "DISC1 had emerged as a candidate risk factor for major mental illnesses, including SCZ, autism spectrum disorder, bipolar disorder and MDD15." (PMID 32066698, 2020). "This is in line with newer evidence demonstrating abnormalities in the gene DISC1 (Disrupted in Schizophrenia 1) in Schizophrenia, Bipolar Disorder and Schizoaffective Disorder." (PMID 30263156, 2016). "Until now, only the rs2492367 polymorphism in DISC1 has been shown to be associated with the bipolar affective disorder; there were no reports about the other SNPs of PTPRB, TRAF3IP3, and DISC1 genes that can affect protein function and disease." (PMID 36397361, 2022).